MYC (MYC proto-oncogene, bHLH transcription factor)
Diseases named in the same sentence as MYC in open-access papers (continued):
Sharing a sentence is not in itself a finding about the gene and the disease.
cancer (continued). "In addition, we included the oncogene MYC, which is under tight control in normal cells, but overexpressed in many cancer types, including HCC." (PMID 34302118, 2021). "Therefore, it has the potential to contribute to more aggressive cancers through MYC-dependent proliferation." (PMID 34298819, 2021). "MYC is a well-known oncogene that is deregulated in many cancers, including MM." (PMID 34885058, 2021). "Notably, MYC functions to amplify the entire gene expression program, which is a critical step for generating transcriptional addiction in cancers." (PMID 34432948, 2021). "MYC also plays a key role in modulating the death response in cancer cells." (PMID 34283054, 2021). "We calculated the half-time of MYC inactivation (t1/2 = 1.04 h) and the corresponding inactivation rate (koff = (ln 2)/t1/2 = 16.01 day-1), which was significantly faster than the observed cancer cell doubling time (1–2 days)." (PMID 33446671, 2021). "TNF, BRCA2, MYC, and IL6 are some examples of proteins that are frequently associated with PCa and are also known to function as biomarkers for other types of cancer." (PMID 34771740, 2021). "A1-mediated altered translation has been implicated in cellular proliferation and cancer, where growth factor receptors and oncogenes like FGF-2 (fibroblast growth factor 2), MYC (c-Myc), IQGAP1 (IQ motif containing GTPase activating protein 1), and CYLD (cyclin D1) are aberrantly translated." (PMID 34439945, 2021). "As we have mentioned, FBW7 agonist leads to the degradation of c-MYC and cyclin E in cancer cells." (PMID 34106407, 2021). "Targeting WDR5 may, thus, provide a strategy to exploit MYC, a critical driver of many cancers that has remained difficult to target directly due to its lack of defined small molecule binding sites." (PMID 34299488, 2021). "MYC is the main regulator of cell metabolism and proliferation, high constitutive expression of which drives many types of tumors, and often correlated with cancer invasion and poor prognosis." (PMID 33771165, 2021). "Some notable examples are: the role of RAS and PI3K pathways in prostate and breast cancers and their therapeutic responses, the Wnt signaling pathway in colorectal and other cancers, the Hippo pathway in melanoma, and the MYC pathway in prostate cancer progression and treatment response." (PMID 34408770, 2021). "Some studies showed that the induction of miR-135a expression in different types of cancers could suppress cell proliferation through target genes (c-MYC, STAT6, SMAD5, and BMPR2)." (PMID 34377051, 2021). "Herein, we demonstrate that small-molecule kinase inhibitor DCLK1-IN-1 strongly inhibits DCLK1 phosphorylation and downregulates pluripotency factors and cancer stem cell (CSC) or epithelial-mesenchymal transition (EMT)-associated markers including c-MET, c-MYC, and N-Cadherin in RCC cell lines." (PMID 34830884, 2021). "As shown in clinically relevant transgenic mouse models, MYC driven cancers are oncogene addicted." (PMID 33446671, 2021). "Thus, we successfully generated a system for inducible, selective, and bidirectional modulation of the MYC−HCF-1 interaction in the context of an archetypal MYC-driven cancer cell line." (PMID 33416496, 2021). "Most of them have been shown to suppress c‐MYC expression and induce apoptosis in cancer cells." (PMID 34138492, 2021). "The inhibition of MYC sensitized cancer cells to DNA damage." (PMID 34683150, 2021). "The MYC gene has been confirmed to be a key oncogene affecting many malignant tumors." (PMID 33540574, 2021). "Several oncogenes, including MYC, phosphoinositide-3-kinase (PI3K), KRAS, protein kinase B (AKT), mechanistic target of rapamycin (MTOR), and HIF-1, are implicated in the regulation of cancer metabolic reprogramming." (PMID 34770949, 2021). "YTHDF1 promotes cancer cell growth through upregulation of MYC." (PMID 33922187, 2021).
cancer (continued). "In addition, PD-L1 mRNA and protein, as well as both O-GlcNAcylated and total cMYC proteins, were suppressed by MTHFD2-KD and recovered by exogenous UTP/UDP in cMYC-overexpressing cancer cells, all of which were compromised in MYC-T58A-overexpressing cells." (PMID 33782411, 2021). "Moreover, assessing the effects of FTH1 on c‐MYC expression was of particular interest given that the latter is known to downregulate FTH1 expression in cancer cells." (PMID 34551213, 2021). "However, Cas13d is highly expressed in cancer cells and with the guidance of crRNA targeting MYC mRNA, Cas13d binds to MYC mRNA results in degradation of MYC expression at mRNA and protein levels." (PMID 33816560, 2021). "MTBP could promote human cancer cells’ proliferation or metastasis by functioning as a co-activator of c-MYC (cellular-myelocytomatosis viral oncogene) or ZEB2 (Zinc Finger E-Box Binding Homeobox 2)." (PMID 34249768, 2021). "Glutamine deprivation in MYC-overexpressing cancer cells results in MYC-dependent apoptosis." (PMID 34638444, 2021). "MYC overexpression is also a key pathway in driving cancer malignancy." (PMID 34001163, 2021). "Additionally, compared with para-cancer tissues, we found that MYC was highly expressed in BC tissues by IF." (PMID 34116677, 2021). "Thus, in order to evaluate a putative role of c-MYC in cancer initiation and progression we next intensified our model and applied high caloric WD to alb-myctg mice." (PMID 35008356, 2021). "Notably, the copy-number events exhibiting higher prevalences in young adult cancers were mainly amplifications, including YAP1 (FDR = 0.027) and MYC (FDR = 6.94E-4), significantly associated with young adult CESC and OV, respectively." (PMID 34788626, 2021). "Since overexpression or amplification of MYC/MYCN and activation of mTOR signaling are often associated with chemoresistance in many cancers including NB, we also wanted to see whether inhibition of these signaling pathways helps to chemosensitize NB cells." (PMID 34565342, 2021). "MS67 potently and selectively depleted WDR5 and was more effective than WDR5 PPI inhibitors in suppressing transcription of WDR5-regulated genes, decreasing the chromatin-bound fraction of MLL complex components and c-MYC, and inhibiting the proliferation of cancer cells." (PMID 34586829, 2021). "Because our data indicate a role of H2A.Z.1 in the maintenance of cell proliferation via MYC regulation, we reasoned that these results could have important implications in cancer." (PMID 34423893, 2021). "Finally, MYC expression was increased in patients who exhibited residual cancer burden score of I, II and III." (PMID 34620206, 2021). "The question therefore remained as to whether endogenous levels of the pro-survival proteins would be sufficient to sustain the malignant growth and survival of MYC-induced cancers." (PMID 33799592, 2021). "Pharmacological inhibition of the bromodomain and extraterminal (BET) family of chromatin adapter proteins has proven effective in this regard, suppressing growth of diverse cancer types mainly through downregulation of the c-MYC oncogene, and its downstream transcriptional program." (PMID 33712563, 2021). "Given estimates that the SCF complex targets hundreds to thousands of proteins, it is possible that the aberrant regulation (i.e., turnover) of additional protein substrates, such as P27, RAD51, c-MYC may also contribute to cancer pathogenesis." (PMID 35008511, 2021). "In addition, MYC and NDRG1 genes located at this locus were also associated with HRD in a pan-cancer manner." (PMID 34976815, 2021).
cancer (continued). "One strategy that might overcome all these obstacles is to exploit cellular dependencies uniquely induced by MYC in cancer cells." (PMID 33760847, 2021). "While HIF1α and c-MYC may compete for binding sites of target genes, the elevated HIF2α level promotes c-MYC activity in a variety of cell lines and in cancer stem cells (CSCs)." (PMID 34575682, 2021). "In addition, the MYC gene has been known as an oncogene that promotes cancer cell growth and proliferation." (PMID 34439333, 2021). "In support of this hypothesis, a novel potent ATP‐competitive inhibitor of CLK2 (T‐025; N2‐methyl‐N4‐[pyrimidin‐2‐ylmethyl]‐5‐[quinolin‐6‐yl]‐7H‐pyrrolo[2,3‐d]pyrimidine‐2,4‐diamine) exhibited particular efficacy in MYC amplified cancer cell lines." (PMID 34092037, 2021). "In some human cancers, the MYC loci can also be disrupted by chromosomal translocations." (PMID 33799592, 2021). "Their high levels of expression in cancer cells may reflect their regulation by MYC as MYC binds to the SHMT2 and MTHFD2 gene promoters, along with that for MTHFD1L." (PMID 35008360, 2021). "We posit that this may be particularly relevant in cancer cells, where enhancers’ invasion by MYC may orchestrate pervasive oncogene-driven transcription and 3D-chromatin remodeling." (PMID 34201047, 2021). "Deregulation of MYC oncogene has been shown to contribute to more than half of human cancers." (PMID 34372899, 2021). "A clear correlation exists between deregulated MYC function and cancer development and progression." (PMID 33801599, 2021). "Gene Set Enrichment Analysis (GSEA) of the genes related to SELPLG in ALCL setting mainly detected genes involved in pathways and cellular functions specifically deregulated in cancer, including MYC and E2F target gene sets, apoptosis and programmed cell death." (PMID 34204843, 2021). "First, the response of PDAC cells to SUMO inhibitors must be analysed in greater functional detail, which might additionally allow to characterise the MYC-hyperactivated cancers with very high sensitivity towards SUMO inhibition." (PMID 33071285, 2021). "It has been reported that the spliceosome is a new target of carcinogenic stress in MYC-driven cancer, and some components of the spliceosome could provide a novel treatment entry point for MYC-driven cancer." (PMID 33550985, 2021). "Based on these results, we hypothesize that while MYC may be the cancer driver, co-amplification of RRM2B and other 8q-genes may be relevant for cancer cell survival." (PMID 33868369, 2021). "By administration of doxycycline, MYC is inactivated quickly and the cancers regress." (PMID 33446671, 2021). "Blocking DYRK2 by curcumin could prevent MYC phosphorylation, which is indispensable for cancer cell growth and consequently inhibit cell transformation." (PMID 33937075, 2021). "The results also support that simultaneous inhibition of BET and PARP, as well as ATR, especially in context of MYC amplified cancers such as this case, might result in a robust synthetic lethality in HR-reduced cancer cells." (PMID 34084283, 2021). "MYC is one of the most powerful oncogenes found to be deregulated in over half of human cancers." (PMID 35582389, 2021). "However, MYC overexpression renders cancer cells vulnerable to some therapeutics, resulting in collateral vulnerabilities amenable to synthetic lethal targeting approaches." (PMID 35095503, 2021). "Many of the MYC DUBs positively regulate MYC stability and activity and could emerge as important cancer therapeutic targets as well." (PMID 34178666, 2021). "In contrast, the most common and recurrent MYC mutation in cancer, T58I, showed no change in TRRAP binding, despite a significant increase in expression." (PMID 34676047, 2021). "The metabolism of cancer stem cells is dependent on the balance between c-MYC and PGC-1α61." (PMID 34725457, 2021). "Aberrant alternative pre-mRNA splicing plays a critical role in MYC-driven cancers and therefore may represent a therapeutic vulnerability." (PMID 34788094, 2021).
cancer (continued). "It has been reported that the overexpression of MYC gene is one of the most common driving factors of human cancer, and the spliceosome is a new target of oncogenic stress in MYC-driven cancer, so the spliceosome play a significant role in cancer physiology and pathology by mediating gene drive." (PMID 34437425, 2021). "Furthermore, the importance of MYC in context with PCa cancer initiation, metastasis, and the stimulation of embryonic stem cell-like signatures in chemoresistant cancer cells was described and reviewed." (PMID 34445612, 2021). "Indeed, CD47 is upregulated in a number of cancer cells, notably by MYC oncogene, a transcription factor, which binds promotor of cd47 and Pdl-1 genes." (PMID 34925315, 2021). "We conclude that MYC-activated cancers might spread oncogenic signals to remote body locations through EVs." (PMID 34847775, 2021). "If the rate of oncogene inactivation is much slower relative to cancer cell proliferation, then it may be possible for the MYC-On cells to continue growing before treatment takes effect." (PMID 33446671, 2021). "In addition, copy number variants have been shown to drive co-amplification of PVT1 and MYC in numerous cancers." (PMID 33499210, 2021). "Thus, many kinases can negatively regulate FBXW7 stability by promoting its self-ubiquitination, which indicates a potential therapeutic strategy against MYC-driven cancer." (PMID 33494392, 2021). "The MYC-centered module (mMYC) showed high prognostic performance in both datasets; MYC was significantly overexpressed in human cancers, and it promotes cell proliferation, sensitizes to apoptosis, and induces cells to undergo apoptosis (Massó-Vallés and Soucek, 2020)." (PMID 36303724, 2021). "Due to its low toxicity, CPX may have potential as a cancer-targeted drug that indirectly targets MYC." (PMID 35186950, 2021). "A broad-reaching mechanism for TRIB1 overexpression could be the location of TRIB1 within the common cancer amplicon 8q24, which also contains the oncogene c-MYC." (PMID 34205360, 2021). "In addition, our network-based approach suggests that known oncogenic hub genes such as KRAS and MYC are prime targets for disruption in cancer cells." (PMID 34662337, 2021). "Insulin-like growth factor 2 mRNA-binding proteins (IGF2BPs; IGF2BP1/2/3), as a newly discovered m6A regulator in recent years, promotes the stability and storage of its target mRNA (such as MYC) in an m6A-dependent manner, and has a carcinogenic effect in cancer." (PMID 34206803, 2021). "We assayed if human cancer-derived cells with abundant MYC were sensitive to diMF and whether overexpression of MYC was necessary for sensitivity." (PMID 33760847, 2021). "Furthermore, additional driver mutations such as in MYC, BCL2, MMSET and FGFR3 are considered as important driver mutations in the development of cancer." (PMID 33572851, 2021). "A recent TCGA pan-cancer analysis found MYC paralogs to be amplified in 28% of all samples." (PMID 34236315, 2021). "MYC deregulation is a signature of many types of human cancers." (PMID 33801599, 2021). "c-Myc [MYC] is one of the most frequently deregulated transcription factors in cancer." (PMID 33651821, 2021). "c-MYC can regulate PTB1 to promote cancer progression and the Warburg effect." (PMID 34887764, 2021). "In addition, overexpression of SKP2 correlates with the reduction of TRUSS in human cancers, suggesting an interplay of MYC Ub ligases in tightly controlling MYC stability during the cell cycle." (PMID 34178666, 2021). "Interestingly, the oncogene c-MYC, known to interact with HIF1α to enhance glycolysis in cancer cells, was correlated to the expression of PDHK1 in our data." (PMID 33668151, 2021). "MYC is a transcription factor and contributes to the development of many cancer types." (PMID 34408775, 2021). "In addition, YY1 regulates the expression of many cancer-related genes such as MYC (alias c-myc) and c-Fos." (PMID 34063990, 2021).
cancer (continued). "MYC and HIF1α are critical in human cancer pathogenesis through regulation of metabolism, angiogenesis, cell proliferation and apoptosis, and self-renewal of cancer stem cells." (PMID 33572152, 2021). "Known oncogenes such as MYC were expressed at a high level across nine types of cancer cells." (PMID 33658503, 2021). "As for AURKA, WDR5 is emerging as a novel promising MYC vulnerability in cancers." (PMID 34884690, 2021). "The stimulatory roles of MYC on cancer progression have been well studied." (PMID 34789315, 2021). "High expression of the MYC gene is characteristic of many types of cancers." (PMID 34440124, 2021). "Alterations in MYC genetics have been described in a variety of cancer types." (PMID 34503295, 2021). "Hence, we expect it is only a matter of time before such combinations are explored in the clinic, with the hope they can provide benefit for the many cancers that depend on the co-operativity between MYC and BCL-2 proteins." (PMID 33799592, 2021). "Oncogene c-Myc (referred in this report as MYC) promotes tumorigenesis in multiple human cancers." (PMID 33791309, 2021). "In addition, the link shown by COSMOS between NFKB1 and MYC can have implications for the treatment of ccRCC, due to its pivotal role in arsenite (a drug used in chemotherapy) treatment of cancer." (PMID 33502086, 2021). "Despite the crucial recent increase in MAFLD and MAFLD-associated cancer, the specific link between c-MYC and MAFLD has not yet been addressed." (PMID 35008356, 2021). "Indeed, their reprogramming potential further signifies the oncogenic role of MYC genes, explaining their dysregulation in up to 70% of human cancers." (PMID 35008802, 2021). "For instance, the hub nodes MYC, NOTCH1 and SHH have been associated to different types of cancer." (PMID 33632303, 2021). "In cancer, prolonged overexpression of MYC could lead to chronic deregulation involving all cellular gene expression programs, which become independent of growth stimuli, causing uncontrolled proliferation." (PMID 33801599, 2021). "The MYC oncogene is frequently overexpressed in human cancers." (PMID 35095503, 2021). "As in other cancers, MYC functions as a potent oncogene in epidermal tissue." (PMID 34553848, 2021). "Additionally, the sensitivity to AOA treatment has been described as a hallmark of mutant KRAS in cancer cells, which cooperates with MYC in cancer metabolic reprogramming." (PMID 34503295, 2021). "Besides, alteration of m6A levels also participates in cancer pathogenesis via regulating expression of MYC." (PMID 33853613, 2021). "Constitutive activation of the PI3K/AKT pathway could lead to MYC upregulation, while genomic or proteomic alterations of MYC are associated with resistance to PI3K pathway inhibitors in cancers." (PMID 33777762, 2021). "Taken together, we hypothesize that increased autophagic flux induced by adverse conditions promotes cancer stemness and a high protein level of MYC in ALK+ ALCL." (PMID 34685497, 2021). "c-MYC is located in chromosome 8q24, which is frequently translocated or amplified in cancer." (PMID 33718147, 2021). "The best example is the MYC oncogene, for which many cancer-specific SEs have been described." (PMID 34680347, 2021). "In this context, the fluorquinolone derivative CX-3543 (quarfloxin), which has been the first-in-class G4 ligand to reach phase II clinical trials for cancer, has been demonstrated to affect MYC transcription indirectly, according to such a complex regulatory mechanism." (PMID 34073075, 2021). "MYC is an important proto-oncogene, which is active in many cancers." (PMID 34413873, 2021). "The MYC oncogene has long been an attractive target in cancer therapeutics." (PMID 34638508, 2021).